CA2 (carbonic anhydrase 2)
Diseases named in the same sentence as CA2 in open-access papers (continued):
Sharing a sentence is not in itself a finding about the gene and the disease.
atopic dermatitis (4 papers, 2008 to 2023). "Furthermore, the upregulation of disease-associated biomarkers, such as NELL2, CA2 and CCL26, indicates the prevalence of an immune response in the atopic dermatitis skin model." (PMID 36615633, 2023). "In accordance with the results of the mRNA expression obtained for primary keratinocytes, atopic dermatitis biomarkers such as NELL2, CA2 and CCL26 were significantly elevated in skin models m2 and m3 stimulated with TH2 cytokines (p < 0.05, p < 0.001, respectively)." (PMID 36615633, 2023). "We found that Th2 cytokines did not induce expression of hBD-2 (not shown) but instead could dose-dependently induce the expression of carbonic anhydrase-2 (CA2), a gene previously found to be overexpressed in lesional atopic dermatitis skin under control of Th2 cytokines." (PMID 18523683, 2008).
cervical cancer (4 papers, 2022 to 2025). A primary or metastatic malignant neoplasm involving the cervix. "Studies have found that the molecular typing of pyroptostic‐related genes (PRGs) in cervical cancer can predict prognosis, and the GNAZ/LAG3/IL1B/CA2/SPRR3 risk scoring model has been constructed." (PMID 41025546, 2025). "This study also confirms that SLC2A1 and CA2 are highly expressed, and that CUX1 is weakly expressed, in cervical cancer tissues." (PMID 37042849, 2023). "This study predicts that anti-CTLA-4 therapy may serve as an immunotherapeutic agent for managing cervical cancer and that the expression of CUX1, SLC2A1, and CA2 genes validated by clinical samples may serve as important targets for treatment modalities in cervical cancer." (PMID 37042849, 2023). "However, the expression of CA2, GNAZ, and SPRR3 did not appear to affect cervical cancer prognosis." (PMID 41025546, 2025).
chordoma (4 papers, 2022 to 2023). Chordomas are rare malignant tumors arising from embryonic remnants of the notochord in axial skeleton. "CDK7/12/13 inhibitor and the CA2 inhibitor, Dorzolamide, have been found to inhibit chordoma in vitro and in vivo." (PMID 36185236, 2022). "CA2 (carbonic anhydrase II) has been identified in switched compartments, cell-specific boundaries, and loops of chordomas." (PMID 36439461, 2022). "In addition, they identified carbonic anhydrase II (CA2) as a novel therapeutic target in chordoma." (PMID 36465398, 2022). "A recent multi-omic study of chordoma cell lines identified CA-2 and THNSL2 as potentially druggable genes in chordoma." (PMID 37434245, 2023). "In an integrated multi-omics analysis, CA2 and THNSL2 were identified in the switched compartments, cell-specific boundaries, and loops, indicating their tumorigenic roles in chordoma." (PMID 36185236, 2022).
ischemia (4 papers, 2015 to 2025). A hypoperfusion of the BLOOD through an organ or tissue caused by a PATHOLOGIC CONSTRICTION or obstruction of its BLOOD VESSELS, or an absence of BLOOD CIRCULATION. "Transient receptor potential melastatin 2 (TRPM2) channel is a Ca2+-permeable, redox-activated cardiac ion channel protective in ischemia–reperfusion, but whether it regulates atrial endocrine output under stress is unclear." (PMID 41511308, 2025). "Nonetheless, effects of this altered input may differ regarding CYP1B1 expression, as CA2 possesses an innate resistance to ischemia and TBI relative to other subregions." (PMID 35054909, 2022). "It is known that myelin damage can be receptor‐mediated and recently oligodendrocytes have been shown to express Ca2+‐permeable Transient Receptor Potential Ankyrin‐1 (TRPA1) channels, whose activation can result in myelin damage in ischemia." (PMID 36762504, 2023).
amyotrophic lateral sclerosis (3 papers, 2016 to 2023). Amyotrophic lateral sclerosis (ALS) is a neurodegenerative disease characterized by progressive muscular paralysis reflecting degeneration of motor neurons in the primary motor cortex, corticospinal tracts, brainstem and spinal cord. "Since DREAM serves as a Ca2+-sensor transcription factor in neurons, it can also participate in the progression of several neurodegenerative disorders, including Alzheimer’s (AD) and Huntington’s (HD) disease, and amyotrophic lateral sclerosis (ALS)." (PMID 37298129, 2023). "CA1 protein levels were preferentially increased in the spinal cord of patients with amyotrophic lateral sclerosis (ALS), while CA2 did not change in these same patients." (PMID 27809276, 2016).
anemia (3 papers, 2018 to 2023). A reduction in the number of red blood cells, the amount of hemoglobin, and/or the volume of packed red blood cells. "Besides, several targets such as CA2, HMOX1, GSTA1, and NOS2 were closely associated with anemia, which could exhibit significant influences on the therapeutic effects of XSHG." (PMID 29551975, 2018).
atrial fibrillation (3 papers, 2022 to 2024). A disorder characterized by an electrocardiographic finding of a supraventricular arrhythmia characterized by the replacement of consistent P waves by rapid oscillations or fibrillatory waves that vary in size, shape and timing and are accompanied by an irregular ventricular response. "Dysfunction of the ryanodine receptor Ca2+ release channels can also initiate spontaneous diastolic Ca2+ release and induce DADs, which contributes to arrhythmogenic mechanisms in catecholaminergic polymorphic ventricular tachycardia, heart failure and atrial fibrillation." (PMID 36524037, 2022).
COVID-19 (3 papers, 2021 to 2022). A disease caused by infection with severe acute respiratory syndrome coronavirus 2. "The important enzyme CA2 in the sperm differentiation process was considerably reduced in COVID-19 group." (PMID 36685935, 2022). "Here, we selected five significant proteins for COVID-19 non-severe versus severe comparison: heparin cofactor 2 (SERPIND1), thyroxine-binding globulin (SERPINA7), angiotensinogen (AGT), carbonic anhydrase-1 (CA1), and carbonic anhydrase-2 (CA2) for docking study." (PMID 33995121, 2021).
diabetic cardiomyopathy (3 papers, 2011 to 2025). Diabetic cardiomyopathy is a disorder of the heart muscle in people with diabetes. "Our study demonstrates that vosoritide/cGMP-induced PDE2 activation modulates acute pro-arrhythmic Ca2+ events in diabetic cardiomyopathy induced by β-adrenergic stress and I/R, but does not address prevention or reversal of cardiac remodelling of Ca2+ cycling proteins in diabetic cardiomyopathy." (PMID 40965622, 2025). "Downregulation of key Ca2+-handling proteins like sarco(endo)plasmic reticulum Ca2+-ATPase (SERCA)2a and ryanodine receptor (RyR2) is one of the major cause of abnormal Ca2+ homeostasis in diabetic cardiomyopathy." (PMID 22054019, 2011).
gastrointestinal stromal tumor (3 papers, 2013 to 2020). "Parkilla and his collaborators lately suggested CA2 acted as a marker of gastrointestinal stromal tumors." (PMID 32922550, 2020). "Before anoctamins (TMEM16 proteins) were identified as a family of Ca2+-activated chloride channels and phospholipid scramblases, the founding member anoctamin 1 (ANO1, TMEM16A) was known as DOG1, a marker protein for gastrointestinal stromal tumors (GIST)." (PMID 30893776, 2019).
ischemic stroke (3 papers, 2023 to 2025). A stroke disorder caused by obstruction of blood flow to the brain, due to thrombotic (local blood clot formation) or embolic (due to a blood clot or other material traveling from another site) event. "Upregulated Trpv4 (log2FC = 1.28), which encoded a Ca2+ channel that mediates Ca2+ influx into the cell during ischemic stroke, exerted injurious effects." (PMID 39224379, 2024).
lactic acidosis (3 papers, 2019 to 2024). Metabolic acidosis characterized by the accumulation of lactate in the body. "Tumor endothelial cells proliferate under lactic acidosis caused by tumor cell glycolytic metabolism, and the pH regulator, carbonic anhydrase 2 (CAII), is involved in resistance to low pH in tumor endothelial cells." (PMID 38576482, 2024).
malaria (3 papers, 2012 to 2023). Malaria is a serious and sometimes fatal disease caused by a parasite that commonly infects a certain type of mosquito which feeds on humans. "Four proteins (CA2, CKB, CKM, DAPK1) were only found to be associated with severe compared to mild malaria." (PMID 30442134, 2018).
mood disorder (3 papers, 2012 to 2021). A cognitive disorder a disturbance in which the person's mood is hypothesized to be the main underlying feature. "Considering the suggested contribution of CA2 to episodic memory, this cellular effect of AVP may contribute to the central influence of this neuropeptide in memory and mood disorders." (PMID 23236353, 2012).
type 2 diabetes (3 papers, 2017 to 2025). "Finally, we will explore the relevance of the Sec61 complex as a Ca2+-leak channel in various pathophysiological (ER stress, apoptosis, ischemia-reperfusion) and pathological (type 2 diabetes, cancer) settings." (PMID 36277220, 2022).
airway hyperresponsiveness (2 papers, 2020 to 2022). "TNFα/IFNγ augmented the expression of several genes that were also corticosteroid insensitive including, CD38, a Ca2+ regulatory protein that contributes to ASM hypercontractility and airway hyperresponsiveness." (PMID 35578269, 2022). "Carbonic anhydrase II (CA2), which was negatively correlated with miR-26a-5p and significantly upregulated in exacerbated horses, is known to be upregulated by Th2 cytokines like IL-4 and IL-13, and reportedly promotes airway hyperresponsiveness." (PMID 32998415, 2020).
allergic asthma (2 papers, 2020 to 2023). A asthma with a basis in a pathological type I hypersensitivity reaction. "On the other hand, our recent study also demonstrated that a small GTPase RhoA, a Ca2+-sensitizing protein that contributes to the augmented BSM contraction in allergic asthma, is one of the targets of miR-140-3p." (PMID 33121100, 2020). "Among them, SLC39A8, ALOX15, and CA2 showed higher expression, while SLC40A1 and C3 exhibited lower expression in patients with allergic asthma." (PMID 37123407, 2023).
argyrophilic grain disease (2 papers, 2021 to 2025). A tauopathy characterized pathologically by the presence of silver stain positive lesions called argyrophilic grains, oligodendrocytic coiled bodies, and neuronal tau-positive pretangles. "However, a predominance of CA2 tau is observed in other diseases such as PART, CBD, PSP, and argyrophilic grain disease (AGD)." (PMID 33980303, 2021).
astrocytomas (2 papers, 2020 to 2023). "On the other hand, endothelial CA2 expression seems to be a common phenomenon among high-grade diffusely infiltrating astrocytomas and is also found to correlate with a poor prognosis." (PMID 38139457, 2023).
autosomal dominant polycystic kidney disease (2 papers, 2013 to 2023). Autosomal dominant form of polycystic kidney disease. "The clue that cilia could be involved not only in the generation but also the sensation of nodal flow came from the genetic analysis of mice mutant for Pkd2, a Ca2+ permeable ion channel involved in the pathogenesis of autosomal dominant polycystic kidney disease (ADPKD) in man." (PMID 23720541, 2013). "Recent studies in patients with autosomal dominant polycystic kidney disease (ADPKD) showed that ablation of cardiac TRPP channels leads to an upregulation of action potential-repolarizing K+ currents, decrease in L-type Ca2+ channel density, and reduction in APD and SERCA activity." (PMID 36902065, 2023).
cardiomyopathy (2 papers, 2023 to 2024). A disease of the heart muscle or myocardium proper. "Additionally, a knowledge graph analysis identified 59 of the 128 Ca2+-regulating proteins as involved in OS-related cardiac diseases, with cardiomyopathy emerging as the predominant category." (PMID 39594561, 2024).
catecholaminergic polymorphic ventricular tachycardia (2 papers, 2020). Catecholaminergic polymorphic ventricular tachycardia (CPVT) is a severe genetic arrhythmogenic disorder characterized by adrenergically induced ventricular tachycardia (VT) manifesting as syncope and sudden death. "Mutations in genes encoding Ca2+ channels or regulators of Ca2+ homeostasis have been shown to cause inherited arrhythmogenic diseases such as catecholaminergic polymorphic ventricular tachycardia (CPVT), Brugada syndrome, Timothy syndrome, and long and short QT syndromes." (PMID 32878278, 2020).
chronic kidney disease (2 papers, 2021). Impairment of the renal function secondary to chronic kidney damage persisting for three or more months. "Iron deficiency is common in chronic kidney disease (CKD), and previous studies demonstrated that iron deficiency enhanced activity of the Ca2+-permeable cation channel on erythrocyte and triggered eryptosis." (PMID 34657570, 2021). "In chronic kidney disease, hyperphosphatemia upregulates the Ca2+ channel ORAI and its activating Ca2+ sensor STIM in megakaryocytes and platelets." (PMID 33804889, 2021).
dementia (2 papers, 2010 to 2019). Loss of intellectual abilities interfering with an individual's social and occupational functions. "Collectively, this supports the role of a hypothetical connection between CA2 and Ch2, where CA2-subregional Lewy pathology could have led to retrograde neurodegeneration of the cholinergic cells in nvlDBB, leading to dementia in PD." (PMID 31023342, 2019). "The data was further validated using specific antibodies to 4 proteins (CA2, GS, CKMT and CRMP2) by western blot (WB) in the same samples used for 2D-DIGE, with additional confirmation by immunohistochemitsry (IHC) using frontal lobe tissue from different HAD and HIV+ non-dementia patients." (PMID 20573273, 2010).
endometrial cancer (2 papers, 2022 to 2023). Primary or metastatic malignant neoplasm involving the endometrium (mucous membrane that lines the endometrial cavity). "Studies have shown that CACNA2D3/CA2 + induces phosphorylation of p38 MAPK in endometrial cancer, which in turn induces apoptosis in tumor cells." (PMID 36624463, 2023). "Activation of GPCR, HER-2 and integrin receptors, leading to PI3K and PKA activation, leading to oxidative phosphorylation and CA2+ signaling, leading to EMT and senescence, are implicated in endometrial cancer metastasis, along with ER-mediated transcription and loss of PTEN activation." (PMID 35328698, 2022).
hypospadias (2 papers, 2013 to 2022). Hypospadias is the displacement of the urethral meatus on the ventrum of the penis. "This was associated with increased mRNA expression of Ca2+ channels important in regulating VSMC Ca2+ influx, specifically CACNA1C (P = 0.03), IP3R (P = 0.007), TRPM2 (P = 0.001), SERCA (P = 0.008), and RyR1 (P = 0.01) in boys with hypospadias vs. controls." (PMID 35567552, 2022).
kidney cancer (2 papers, 2024 to 2025). Primary or metastatic malignant neoplasm involving the kidney. "Several genes showed a low gDS in most kidney cancer cell lines, such as CD82, CD7, MEST, SELP, BMP6, CA2, DNAJC6, and VEPH1." (PMID 38728235, 2024).
mesothelioma (2 papers, 2019). A usually malignant and aggressive neoplasm of the mesothelium which is often associated with exposure to asbestos. "Moreover, the changes in the expression and/or activity of Ca2+ permeable ion channels seem to be a distinguishing sign of mesothelioma cells." (PMID 31766522, 2019).
metabolic syndrome (2 papers, 2020 to 2023). A cluster of metabolic risk factors for CARDIOVASCULAR DISEASES and TYPE 2 DIABETES MELLITUS. "In conclusion, the subchronic administration of rosuvastatin to rats with metabolic syndrome improved the acetylcholine-induced relaxant response, involving stimulation of the NO/cGMP/PKG/Ca2+-activated K+ channel pathway." (PMID 32049102, 2020).
migraine (2 papers, 2020 to 2022). "TRPM8, which functions as a Ca2+-permeable channel, requires the assembly of functional homologous tetramers and plays a vital role in environmental cold sensing, menthol-induced analgesia of acute and inflammatory pain, and migraines." (PMID 35665750, 2022).
muscle disorders (2 papers, 2020 to 2022). "RYR1-related myopathy is a class of rare muscular diseases due to heterozygous or homozygous mutations in RYR1, which encodes the Ca2+ channel RYR1." (PMID 36450915, 2022). "In skeletal muscles, TRPV1 operates as a reticular Ca2+-leak channel and several TRPV1 mutations have been associated with two muscle disorders: malignant hyperthermia (MH) and exertional heat stroke (EHS)." (PMID 33036239, 2020).
ocular hypertension (2 papers, 2012 to 2025). Abnormally high intraocular pressure. "AAV-Cas13d-mediated AQP1 and CA2 knockdown was tested in a dexamethasone-induced ocular hypertension model." (PMID 40575705, 2025). "The present study demonstrates that simultaneous knockdown of AQP1 and CA2 in the ciliary body lowers IOP in wild-type mice and a steroid-induced ocular hypertension mouse model." (PMID 40575705, 2025). "We previously reported that calcineurin, a Ca2+/calmodulin-dependent serine/threonine phosphatase, is activated and proposed that it participates in retinal ganglion cell (RGC) apoptosis in two rodent ocular hypertension models." (PMID 23233785, 2012).
osteosarcoma (2 papers, 2004 to 2023). A usually aggressive malignant bone-forming mesenchymal neoplasm, predominantly affecting adolescents and young adults. "In the present study, we have demonstrated that the Ca2+-binding protein S100A4 sensitizes human osteosarcoma cells to IFN-γ-induced apoptosis." (PMID 15318945, 2004).
rectal cancer (2 papers, 2015 to 2023). A primary or metastatic malignant neoplasm that affects the rectum. "The most positive correlation was observed with the CA2 gene expression for Act_DC (rho = 0.356, p = 4.43 × 10−15) in colon and Act_DC (rho = 0.38, p = 3.92 × 10−7) in rectal cancer." (PMID 37895185, 2023).
retinal dystrophies (2 papers, 2020 to 2023). "Interestingly, genes involved in microphthalmia (VAX1, ALDH1A3, GJA1, and SMOC1) and retinal dystrophies (ADAMTS9, KCNJ13, CA2 and ABCA4) were also selected." (PMID 37479765, 2023).
Sepsis (2 papers, 2021 to 2025). Sepsis is defined as life-threatening organ dysfunction caused by a dysregulated host response to infection. "In addition, carbonic anhydrases IV and II (CA4 and CA2), which produce H2CO3, were upregulated in sepsis." (PMID 40699834, 2025).
ulcerative colitis (2 papers, 2021 to 2022). An inflammatory bowel disease involving the mucosal surface of the large intestine and rectum. "CA2 is lowly expressed in ulcerative colitis and CRC tissues, and low CA2 expression is associated with a better prognosis." (PMID 36338624, 2022).
viral infection (2 papers, 2016 to 2022). "Other novel studies show that viral infections may precipitate ferroptosis by hijacking Ca2+ channels and pumps, suggesting a role for calcium channel blockers in the treatment of viral infections." (PMID 35645713, 2022).
age (1 paper, 2020). A temporal measurement of the time period elapsed since an identifiable point in the life cycle of an organism. "Cells express a unique pattern of Ca2+ channels and pumps geared to fulfill specific physiological requirements and there is a decline in the fidelity of these processes with age and age-associated diseases." (PMID 32884834, 2020).
autism spectrum disorder (1 paper, 2024). A spectrum of developmental disorders that includes autism, and Asperger syndrome. "Furthermore, mutations in NR3C2, the gene that encodes MR, are associated with autism spectrum disorder in humans, further strengthening the implications that MR dysregulation, and perhaps CA2, may be involved in some the behavioral deficits found in certain neurodevelopmental disorders." (PMID 38405991, 2024).
bone marrow failure (1 paper, 2017). "The phenotype of IARO, previously associated with mutations in the PLEKHM1, CLCN7, and CA2 genes, 21, 24, is defined as asymptomatic at birth, with patients exhibiting fractures by the end of their first decade of life, while bone marrow failure and hepato-splenomegaly are rare." (PMID 28592808, 2017).